TRAP1 (TNF receptor associated protein 1)
Diseases named in the same sentence as TRAP1 in open-access papers (continued):
Sharing a sentence is not in itself a finding about the gene and the disease.
cancer (continued). "CCT1, CCT5, and FKBP4 showed significantly lower expression in the cancer patients compared to the healthy volunteers, whereas HSPA9 and TRAP1 showed a significantly higher expression in patients with cancer compared to the control group for the most cancer types." (PMID 34692733, 2021). "In the past few years, TRAP1, the mitochondrial isoform of the heat shock protein 90 (HSP90), has been recognized as an important modulator of mitochondrial bioenergetics of normal and cancer cells." (PMID 31987035, 2020). "Our results highlight that TRAP1 function in metabolism and cancer cannot be understood without a focus on TRAP1 tetramers as potentially the most relevant functional entity." (PMID 31987035, 2020). "In such a way, TRAP1 is able to rewire metabolism by downregulating mitochondrial oxidative phosphorylation (OXPHOS) and promoting glycolysis, a feature resembling the so-called “Warburg effect” distinctive of cancer cells." (PMID 32411008, 2020). "DN401 degrades client proteins of Hsp90 and TRAP1 without inducing Hsp70 in different cancer cells; this mechanism increases mitochondrial fragmentation and cell apoptosis, thus enhancing the anticancer activity of the drug." (PMID 33575209, 2020). "TRAP1 is a member of the Heat Shock Protein 90 (HSP90) family, the only one showing a predominant but not exclusive mitochondrial localization, having different roles in cancer, neurodegeneration and other apparently unrelated diseases." (PMID 29621137, 2018). "In the reverse approach, overexpression of TRAP1 in non-transformed fibroblasts reduced mitochondrial respiration and mimicked the respiratory pattern of cancer cells." (PMID 29621137, 2018). "In line with this hypothesis, we have recently shown that TRAP1 limits ROS generation by SDH, aka the complex II of the respiratory chain, thus increasing the threshold for PTP opening in cancer cells and protecting them from death stimuli." (PMID 28405578, 2017). "Based on our recent observation that BRAF is a client protein of TRAP1, an HSP90 molecular chaperone upregulated in several human cancers including CRC, we evaluated the molecular mechanisms responsible for resistance to apoptosis induced by BRAF activation in human CRCs." (PMID 26084290, 2015). "Therefore, we investigated whether macrophages could tune key cancer cell features upon exposure to MPNST-CM, and if TRAP1 presence could influence their pro-tumoral properties." (PMID 40877908, 2025). "In an attempt to dissect common alterations in the central carbon metabolism of cells lacking TRAP1 (compared to isogenic WT cells), multiple cancer-derived cell lines were grown in otherwise non-limiting conditions but were limited as to the carbon sources that feed glycolysis and OxPhos." (PMID 35883436, 2022). "Furthermore, a subsequent analysis on the possible role of the altered genes in CRC and IPD data sets in the survival of cancer patients (TCGA-COAD data sets) pointed to a significant influence on survival for eight of these genes (TUBB6, PAK6, SULT1A1, SLC11A1, TRAP1, FAM50B, SPON2, FES)." (PMID 34885088, 2021). "Although there are not yet publications directly linking TRAP1 and the elevated radioresistance of hypoxic tumors, such links seem highly likely, as TRAP1 activity may potentiate the antioxidant capacity of cancer cells adapted to hypoxia." (PMID 33806538, 2021). "TRAP1 seems to be a promising target for anti-CSC therapy because inhibiting this chaperone may prevent CSC phenotype formation through EMT, as well as eliminating existing CSCs or sensitizing them to the conventional treatment of cancer." (PMID 32268506, 2020). "For Trap1, our results further emphasize the importance of the context and support the argument that targeting Trap1 may not be beneficial in all types of cancer at all stages and in all circumstances." (PMID 28407697, 2017).
cancer (continued). "Future studies will determine whether these differences reflect non-overlapping functions of mitochondrial Hsp90 versus TRAP1 in enabling mitochondrial reprogramming in cancer." (PMID 29348817, 2017). "Similarly to the reported interactions, we find that TRAP1 interacts with CypD and VDAC1 (but not ANT) in our pan-cancer analysis." (PMID 32235444, 2020). "Accordingly, here we observe that a low concentration of 3-NP down-modulates the amount of mitochondrial superoxide anion in cells expressing low TRAP1 levels (either shTRAP1 cancer cells, or mock MEF cells), whereas it is not effective in cells with high TRAP1 levels." (PMID 25564869, 2014). "Whether these vector integrations facilitate the proliferation of clones remains unclear because these genes in the dominant clones (LOC100130950 and TRAP1 in Pt1 and SMARCC1 in Pt2) were not categorized as cancer genes, or their expression levels did not increase." (PMID 34786435, 2021). "TRAP1 (HSP75 or HSC5)—a 75 kDa member of the HSP90 subfamily—is an ATP-utilizing molecular chaperone localized to mitochondria and participating in the regulation of proliferation, apoptosis, differentiation, and energetic metabolism in both normal and cancer cells and non-stem ones." (PMID 32268506, 2020). "Notably, cells with low TRAP1 levels (shTRAP1 cancer cells or mock MEFs) were unable to form colonies in soft agar; anti-oxidants (both NAC and Trolox) rescued their tumorigenic potential, while they could not further increase colonies in TRAP1-expressing cells." (PMID 25564869, 2014).
tumor (103 papers, 2008 to 2025). "METHODS: We evaluated TRAP1’s clinical relevance for prognostic predictions and its association with tumor immunity and metabolism." (PMID 41422190, 2025). "Tumor necrosis factor receptor-associated protein 1 (TRAP1) plays a vital role in different tumor types and is a significant member of the mitochondrial heat shock protein 90 (Hsp90) family." (PMID 38802732, 2024). "Inhibition of TRAP1 in tumor cells caused marked increase in lysosome content and autophagy activity." (PMID 38098505, 2023). "TRAP1 attenuation or loss of phosphorylation at these residues prevents tumor growth, in a succinate-dependent manner." (PMID 35740911, 2022). "For example, heat shock protein 90 (HSP90) and its homolog TNF receptor-associated protein-1 (TRAP-1) are extensively involved in the mitochondrial chaperone network in tumor cells that controls protein folding quality." (PMID 35269393, 2022). "Masuda and colleagues reported that induction of apoptosis by β-hydroxyisovalerylshikonin (β-HIVS) and topoisomerase II inhibitor VP16 in tumor cell lines is associated with the reduction in TRAP-1 expression." (PMID 35127545, 2022). "As for Trap-1, this mitochondrial isoform has association with tumor metabolism and mitochondrial homeostasis." (PMID 36010632, 2022). "The tumor theranostic utilizing Gamitrinib enhanced specific tumor apoptosis through inhibiting TNF receptor-associated protein-1 (TRAP-1) chaperones." (PMID 34717757, 2021). "Trap1−/− mice showed a reduced incidence of age-associated pathologies, including inflammatory tissue degeneration and spontaneous tumor formation." (PMID 34829705, 2021). "This study also proposed that TRAP1 causes tumor cells to invade stromal tissue by inducing epithelial-mesenchymal transition (EMT), which is implicated in the metastasis of primary tumors." (PMID 33575209, 2020). "In this case, we provide a novel strategy to inhibit tumor growth by simultaneous activation of liver-X-receptors and interference with Tumor Necrosis Factor Receptor-associated Protein 1 (TRAP1)." (PMID 31181660, 2019). "The observation that TRAP1 is implicated in the regulation of tumor cell cholesterol synthesis is novel and in support of the notion that TRAP1 in certain contexts (as in the current one) acts as an oncogene." (PMID 31181660, 2019). "But, TRAP1 expression was marginally associated with lymph node involvement and tumor differentiation (p = 0.085, p = 0.082, respectively)." (PMID 28088229, 2017). "Recently, the mitochondrial molecular chaperone TRAP1 (tumor necrosis factor receptor associated protein 1) was identified as a key regulator of mitochondrial bioenergetics in tumor cells, with a profound impact on neoplastic growth." (PMID 28405578, 2017). "At molecular level, downregulation of TRAP1 associates with higher expression of p70S6K, a kinase frequently active in OC with emerging roles in cell migration and tumor metastasis." (PMID 27977010, 2016). "Silencing of TRAP1 in tumor cells also causes mitochondrial swelling, loss of ψm, rapid increase in intracellular ROS generation and release of cytochrome C, identical to the effects of PINK1 knockdown." (PMID 18560593, 2008). "In the NSCLC cell line A549, CVM-1125 reduces cytosolic succinate levels and causes destabilization of HIF-1α by targeting TRAP1, thereby blocking its downstream signaling and ultimately inducing mitochondrial apoptosis, inhibiting tumor cell growth, and suppressing angiogenic mimicry." (PMID 38098505, 2023). "In addition, worse tumor differentiation and increasing pathologic N stage were marginally associated with TRAP1 expression (p = 0.085, 0.082, respectively), but they were not statistically significant." (PMID 28088229, 2017). "Functionally, TRAP1 exhibits a dual role: it acts as a cytoprotective factor under physiological stress while also promoting tumor progression." (PMID 41226319, 2025).
tumor (continued). "Instead, administration of exogenous α-KG interferes with the M2-like phenotype acquisition of TRAP1-expressing tumor-conditioned macrophages." (PMID 40877908, 2025). "TRAP1-dependent metabolic rewiring in macrophages is mandatory for sustaining this interplay, as a TRAP1-succinate-HIF-1α signaling axis orchestrates their acquisition of tumor-promoting features." (PMID 40877908, 2025). "We previously demonstrated that TRAP1 enhances tumor progression by downregulating SDH activity and inducing succinate accumulation." (PMID 40424720, 2025). "It is well possible that the pro-neoplastic functions of TRAP1 rely upon the differential interaction with several pools of clients, influencing more than one biological routine required for tumor growth." (PMID 40424720, 2025). "In humans, TRAP1 has been extensively studied and is known to play important roles in tumor cell growth; however, its function in insects remains relatively limited." (PMID 41148932, 2025). "In tumor cells TRAP1 down-regulates SDH activity, installing a pseudo-hypoxic condition sustained by succinate-dependent stabilization of the transcription factor HIF-1α." (PMID 40877908, 2025). "Both GTE and EGCG suppress the expression of TRAP1, Hsp90, and Hsp27, thereby impairing tumor growth and promoting apoptosis." (PMID 41226319, 2025). "During tumor progression, TRAP1 interacts with NRF2, the master regulator of antioxidant defense, to lower ROS levels." (PMID 41226319, 2025). "We have previously found that TRAP1-mediated inhibition of SDH has a pro-neoplastic effect in various tumor cell models." (PMID 40074754, 2025). "Research by the Altieri group reported reduced ATP production and overall tumor cell energy metabolism characterized by reduced glucose utilization and lactate production following TRAP1 knockdown with Gamitrinib." (PMID 39936995, 2025). "It has been shown that post-translational modifications like S-nitrosylation, phosphorylation, and acetylation/deacetylation can modulate TRAP1 activity, influencing its eventual effects on tumor growth." (PMID 40074754, 2025). "A careful study of cancer biology has revealed that tumor cells exhibit high levels of TRAP1 within their mitochondria to maintain protein homeostasis." (PMID 39936995, 2025). "Results also showed that TRAP1 inhibitor gamitrinib containing triphenylphosphine induces cyclophilin D-dependent mitochondrial permeability transition in tumor cells, leading to apoptosis." (PMID 39148727, 2024). "It is known that TRAP1 can overcome metabolic stress and promote tumor cell metastasis by inhibiting the activation of AMPK and then activate mTOR signaling." (PMID 37351538, 2023). "Recent research has found that TRAP1 overexpression (TRAP1 OE) promotes mitochondrial fission, enhanced in vitro migration and in vivo metastasis of tumor cells, and altered cellular homing properties." (PMID 38098505, 2023). "In conclusion, these data allow us to propose a mechanism of action for CVM-1118 in the suppression of tumor growth, induction of cell apoptosis, and inhibition of VM formation–via targeting TRAP1." (PMID 37351538, 2023). "We have encountered the mitochondrial homolog of Hsp90, the TRAP-1, regulating mitochondrial dynamics, metabolism, and tumor metastasis." (PMID 37165028, 2023). "MtHsp90, including Hsp90 and its homologue TRAP1 were abundantly present in the mitochondria of tumor cells." (PMID 38098505, 2023). "So TRAP1 inhibit CypD and preserve the integrity and membrane potential of mitochondria, which is a vital survival mechanism for tumor cells." (PMID 38098505, 2023). "Its expression is correlated with tumor stage, and high expression of TRAP1 correlates with poor survival in colon cancer and NSCLC." (PMID 37351538, 2023). "Biological assays indicate that the mechanism of action of CVM-1118 is via targeting TRAP1 to induce mitochondrial apoptosis, suppress tumor cell growth, and inhibit vasculogenic mimicry formation." (PMID 37351538, 2023).
tumor (continued). "Among Hsp90 homologs, the mitochondrial chaperone TRAP-1 regulates cellular energy metabolism, tumor metastasis, and many more." (PMID 37165028, 2023). "The study also emphasizes TRAP-1’s contribution to anaplerotic mechanisms supporting tumor progression." (PMID 37165028, 2023). "It has been suggested that TRAP1 plays an essential role in reprogramming the mitochondrial pathway to critically support tumor growth." (PMID 38098505, 2023). "Here, we confirmed that treating tumor cells with CVM-1125 reduced the downstream factors of TRAP1 including HIF-1α, Nodal, and Notch." (PMID 37351538, 2023). "in a recent research demonstrated that in tumor cells TRAP1 maintains mitochondrial integrity during glucose deprivation and enhances cellular utilization of glutamine for cellular energy requirements via the HIF2α-SLC1A5-GLS axis." (PMID 38098505, 2023). "Next, they use pooled siRNAs to silence TRAP1, the same effect was reproduced, demonstrating mtHsp90 ‘s importance in tumor cell motility." (PMID 38098505, 2023). "The master antioxidant transcription factor NRF2 was also activated in this model, and given the established role of TRAP1 in regulating intracellular ROS, TRAP1 likely participates in NRF2-driven ROS mitigation during tumor development." (PMID 35740911, 2022). "TRAP1 regulates the metabolic adaptations of tumor cells to the changing conditions experienced in the microenvironment." (PMID 35614131, 2022). "TRAP1 degradation also led to increased SDH activity, in agreement with previous work, and sensitized cells to SDH inhibitors, identifying TRAP1-SNO as a predictor of tumor cell response to this class of drugs." (PMID 35740911, 2022). "Both TRAP1 and CyPD can undergo many PTMs that affect their activity, with a particular relevance in tumor models." (PMID 35614131, 2022). "TRAP1 has complex effects on healthy and tumor cells; therefore, deepening the understanding of its role in different factors’ presence of TRAP1 and its role in the transition from the healthy to the tumor state is crucial to developing new CRC therapies." (PMID 36499214, 2022). "Results also showed that TRAP1-expressing tumor cells have a high level of succinate, resulting in HIF-1α stabilization." (PMID 35127545, 2022). "In turn, HIF1 activation increases TRAP1 expression, and TRAP1 is crucial in maintaining a low oxygen consumption rate under hypoxia, a feature whose importance extends beyond conditions of tumor growth." (PMID 35614131, 2022). "Sciacovelli and co-workers demonstrated that high expression of TRAP1 in tumor cells enhances neoplastic transformation." (PMID 35127545, 2022). "The HSP90/TRAP-1 mitochondrial protein folding system is required for tumor survival and to maintain OXPHOS capacity under starvation or hypoxic conditions." (PMID 35269393, 2022). "Accordingly, the antineoplastic effect of both SIRT3 overexpression and NIC administration is higher in TRAP1 knock-out cells, suggesting that targeting multiple metabolic components can dramatically hit tumor growth." (PMID 35393510, 2022). "Overexpression of TRAP1 in CAFs enhanced maximal respiration and ATP production, which can provide more energy and material sources for cell tumor growth." (PMID 34906113, 2021). "SDH is also regulated by the mitochondrial molecular chaperone TRAP1, which is induced in most tumor types." (PMID 34199098, 2021). "A more recent study showed that the purine scaffold small molecule DN401 simultaneously inhibited all HSP90 paralogs, including HSP90, TRAP1, and GRP94, and synergized the anti-tumor effects with another TRAP1 inhibitor, gamitrnib." (PMID 33898309, 2021). "Identified molecular pathways suggested that TRAP1 is involved in the switch toward aerobic glycolysis of tumours, i.e., decreased OXPHOS activity together with enhanced glucose utilization." (PMID 34769108, 2021).